IFNG (interferon gamma)
Diseases named in the same sentence as IFNG in open-access papers (continued):
Sharing a sentence is not in itself a finding about the gene and the disease.
acute myeloid leukemia (48 papers, 2013 to 2025). Acute myeloid leukemia (AML) is a group of neoplasms arising from precursor cells committed to the myeloid cell-line differentiation. "NK cells expressing TIM-3 show a marked increase in IFNγ production in response to acute myeloid leukemia (AML) blast cells that endogenously express Gal-9." (PMID 25886742, 2015). "Interestingly, ICP+ Vγ9Vδ2 T cells maintain the ability to produce IFNγ and to secrete GzmB and Prf in MM, acute myeloid leukemia (AML), and other cancers." (PMID 37143664, 2023). "Azacitidine (a DNA methyltransferase (DNMT) inhibitor approved for acute myeloid leukemia (AML)) was shown to upregulate PD-1 and IFNγ signaling." (PMID 37631380, 2023). "Another study found that IFNγ secreted by acute myeloid leukemia (AML) cells upregulated IFNγ-dependent genes related to Treg induction, including IDO1, in mesenchymal stromal cells (MSCs)." (PMID 37876966, 2023). "However, while IFNγ levels were elevated in sera of most newly diagnosed acute myeloid leukemia (AML) patients, its complex interplay in AML remains insufficiently understood." (PMID 38418901, 2024). "Alteration of ILC subsets composition in patients with acute myeloid leukemia (AML), compared with the controls, could change the protective function of ILC1s by increasing their frequencies and reducing IFNγ and TNFα." (PMID 32117199, 2019). "Upon stimulation with IFNg, STAT1 activation resulted in PD-L1 upregulation and in reduction of NK-cell activity against tumor cells in multiple myeloma, acute myeloid leukemia (AML), and acute lymphoblastic leukemia (ALL)." (PMID 29765155, 2018). "There is also a strong association between low DNA methylation status of the PD-L1 promoter in tumors and poor survival of acute myeloid leukemia (AML) patients, suggesting that DNA methylation may block the induction of PD-L1 in tumors in response to IFNγ or other immunological cues." (PMID 28545238, 2017). "Furthermore, in acute myeloid leukemia (AML) the low NKG2D expression by NK cells results in an impairment of cell cytotoxicity and leads to IFNγ production." (PMID 34680190, 2021).
Cirrhosis (48 papers, 2008 to 2025). A chronic disorder of the liver in which liver tissue becomes scarred and is partially replaced by regenerative nodules and fibrotic tissue resulting in loss of liver function. "Persistent alterations are observed only in chronic HCV patients with cirrhosis, displaying a distinct long-term pattern compared to IL-10, IL-22, TNFα, IFNγ, and IL-6." (PMID 39578604, 2024). "Stem cells: Compared to controls, LXR/RXR and RICTOR signaling pathways were activated in compensated cirrhosis but inflammatory pathways (IFNG, TNF) were downregulated." (PMID 38369527, 2024). "Recent reports suggested relation between Interferon Gamma (IFN-γ) gene polymorphism and the risk of development of HCC on top of hepatic cirrhosis." (PMID 34181338, 2021). "Patients with increased anti-OSE IgG had a higher prevalence of fibrosis and/or cirrhosis with elevated serum levels of interferon gamma (IFN-γ)." (PMID 34630404, 2021). "A switch to a Th1 pattern of tumor necrosis factor alpha (TNF-a) and interferon-gamma (IFN-γ) production and a concomitant depletion of Th17 in the native layer has been reported in a rat model of liver cirrhosis as cirrhosis progresses into the decompensated phase." (PMID 38191517, 2024). "According to some reports, splenectomy in patients with cirrhosis might improve their impaired immune status by increasing interferon gamma production and reducing programmed cell death protein-1 (PD-1) expression in peripheral CD4+ T cells or CD8+ T cells." (PMID 38647617, 2024). "Furthermore, our data suggest that Aβ constructs that specifically bind to HSC, either alone or in combination with an approach targeting IFNγ and/or NO, might be a potential therapeutic option for the treatment of advanced stages of cirrhosis." (PMID 32089540, 2020). "Patients with HCC with high scores had lower levels of interferon-gamma and CCL8 (false discovery rate <0.05), whereas patients with cirrhosis with high scores showed higher matrix metallopeptidase 2 (MMP2) levels (false discovery rate <0.05)." (PMID 40995436, 2025). "Enterocytes: IPA analysis showed significant activation of inflammatory pathways (TNF, IFNG), PPARG/A with gut-liver signaling pathways (FGF21, IGF1R, CREBP) and fatty acid and lipid oxidation in compensated cirrhosis versus controls." (PMID 38369527, 2024). "Interferon (IFNγ), IL-4, and IL-17 concentrations were the lowest in patients with HCC with cirrhosis." (PMID 38015590, 2023). "The HCC timepoint was characterized by a significant increase in interferon-gamma (IFN-γ), tumour necrosis factor alpha (TNF-α), IL-6 and IL-17 compared to inflammation and cirrhosis timepoints (all P < 0.05)." (PMID 33858327, 2021).
fibrosis (48 papers, 2004 to 2025). the formation of excess fibrous connective tissue in an organ or tissue in a reparative or reactive process. "Two polymorphisms (+2109A/G and +3810A/G) in intron 3 of the IFNγ gene were associated with periportal fibrosis: the 2109G allele with severe fibrosis, and 3810A with protection from fibrosis." (PMID 26540410, 2015). "Two polymorphisms, +2109A/G (rs1861494) and +3810A/G, in intron 3 of the IFNγ gene associated with periportal fibrosis in a Sudanese population: the 2109G allele decreased IFNγ expression and correlated with severe fibrosis, whereas 3810A increased IFNγ expression and protected from fibrosis." (PMID 26540410, 2015). "In relation to cytokine levels in F0 group, statistically significant decrease in group of patients with fibrosis (F1, F3) was recorded for IFNγ (p = 0.039), IL-2 (p = 0.033), IL-17 (p = 0.039) and IL-13 (p = 0.047)." (PMID 31318916, 2019). "Fibrosis can be ameliorated by interferon-gamma (IFN-γ), which is a soluble cytokine showing various effects such as anti-fibrosis, apoptosis, anti-proliferation, immunomodulation, and anti-viral activities." (PMID 31006829, 2019). "Both CXCL10 and IFNγ are increased in patients with MASLD and linked with development of steatohepatitis and fibrosis, which could partially explain their increased levels in septic patients." (PMID 40076848, 2025). "Furthermore, we also tested the effect of lowering IFNG in the FA model of fibrosis by injecting mice with IFNG-neutralizing antibodies." (PMID 36732547, 2023). "By evaluating the responses of 6 inbred mouse strains which provided genetic background diversity in a controlled environmental setting, we identified correlations of lower Il17 and Ifnγ values in lavage as well as increased numbers of infiltrating Th1 and Th17 cells with fibrosis severity." (PMID 25889053, 2015). "Most interestingly, a mouse model of bleomycin-induced fibrosis showed that the administration of human CCL18 via an adenoviral vector increased TNF-, IFNγ-, MMP-2 and MMP-9 expression and increased lymphocytosis but attenuated unexpectedly the bleomycin-induced collagen deposition." (PMID 38334630, 2024). "Higher levels of pro-inflammatory cytokines IFNγ, IL-6, IL-8 and TNFα were found in MASLD with fibrosis patients compared with MASLD without fibrosis." (PMID 38235661, 2024).
Sjögren’s syndrome (48 papers, 2011 to 2025). "Peripherally elevated Th-17 cell activity, with the co-expression of interleukin 17 and interferon gamma, is associated with chronic inflammation characteristic of Sjögren’s syndrome." (PMID 33912165, 2021). "Further support for a role of IFNγ in lymphomagenesis comes from a study of Sjögren’s syndrome, an autoimmune condition associated with a high incidence of marginal zone lymphoma (probably >50-fold greater than for normal subjects)." (PMID 29293620, 2018). "DMSCs improve the immunoregulatory effects on T and B lymphocyte responses based on decreasing CD4+ T lymphocyte proliferation, intracellular Interferon-gamma (IFN-γ), and IL-17 secretion in primary Sjögren’s syndrome." (PMID 37058201, 2023). "The lacrimal gland (LG) of the CD25-/- model of Sjögren’s syndrome (SS) has high interleukin (IL)-17, IL-13 and interferon-gamma (IFN-γ) cytokines." (PMID 25889094, 2015). "Finally, IFNγ as well as type I IFNs may function cooperatively in promotion of Sjogren’s syndrome as shown by upregulation of IFN response genes (IRGs)." (PMID 25601864, 2014). "Ocular surface disease was assessed by quantifying corneal epithelial damage with lissamine green stain in the NOD.H-2h4,IFNγ−/−,CD28−/− (NOD.H-2h4 DKO) mouse model of Sjögren's syndrome (SS)." (PMID 35727180, 2022). "The study aimed to quantify certain cytokines involved in the pathomechanism of primary Sjögren syndrome (IL2, IL5, IL6, IL10, IL13, TNFα, IFNγ) and determine their common clinical correlation." (PMID 36143051, 2022). "Diseases like glaucoma, GvHD, and scleritis biases the immune response to IFNγ release through IL12-mediated Th1 activation, whereas Sjögren’s syndrome activates Th2 immunity." (PMID 31810226, 2019). "Additionally, the bioactive cargo within these EVs, containing cytokines like interleukin-17 (IL-17) and interferon-gamma (IFN-γ), provides insight into the pro-inflammatory environment characterizing Sjogren’s syndrome." (PMID 38473976, 2024). "Moreover, those are present in Sicca syndrome; however, in this condition, the cluster presents low expression of CCL19, most likely reflecting the decreased level of inflammation and lower transcripts of TNFα and IFNγ in Sicca." (PMID 39747819, 2025). "The SOCS and Sjogren’s syndrome reviews as well as others presented here, therefore, are interrelated in terms of approaches to dealing with diseases where IFNγ may play either a positive or negative role." (PMID 25601864, 2014).
dry eye (47 papers, 2011 to 2025). "Interferon-gamma (IFN-γ) has been implicated in conjunctival keratinization and goblet cell loss in dry eye." (PMID 27623073, 2016). "Interferon-gamma can enhance the expression of IFITM1 in the conjunctiva of patients with dry eye syndrome, which may play a role in abnormal terminal differentiation of the epithelium." (PMID 37965330, 2023).
acute respiratory distress syndrome (46 papers, 2008 to 2025). Progressive and life-threatening pulmonary distress in the absence of an underlying pulmonary condition, usually following major trauma or surgery. "Elevated levels of pro-inflammatory cytokines and chemokines (e.g., TNFα, IFNγ, IL-1, IL-6, IL-8, IL-9, IL-12 IL-15, and IL-17) have been found, up to 10 days after the onset of symptoms, in the plasma of patients with acute respiratory distress syndrome (ARDS) caused by influenza A/H1N1." (PMID 32219005, 2019). "Elevated levels of pro-inflammatory cytokines and chemokines (e.g., TNFα, IFNγ, IL-1, IL-6, IL-8, IL-9, IL-12 IL-15, and IL-17) have been found, up to ten days after the onset of symptoms, in the plasma of patients with acute respiratory distress syndrome (ARDS) caused by influenza A/H1N1." (PMID 23148654, 2012). "Systemic inflammatory disorders such as Acute Respiratory Distress Syndrome (ARDS), vasculitis, sepsis, and acute cytokine release syndrome (CRS) induced by CAR-T therapies are associated with increased plasma levels of inflammatory stimuli such as cytokines TNFα and IFNγ." (PMID 40894883, 2025). "The GM-CSF excess rescued mice from an acute respiratory distress syndrome (ARDS)-like illness and stabilized lung mechanical parameters, improved clearance of exudate protein, and disconnected M1 activation by type II IFNγ." (PMID 29304863, 2018). "In a cohort of 35 acute respiratory distress syndrome (ARDS) and 13 sepsis patients, 3 patients showed anti-IL-6 auto-antibodies, two anti-IFNω auto-antibodies, two anti-IFNγ auto-antibodies, and one anti-IL-1α auto-antibodies." (PMID 38203686, 2023).
candidiasis (46 papers, 2007 to 2025). Infection with the organism Candida. "We theorize that as emapalumab blocks IFNγ, subsequently blocking neutrophil activation and IL-6 modulation; it led to our patient being more susceptible to systemic candidiasis, resulting in fungal emboli that led to her intraparenchymal hemorrhage)." (PMID 40407638, 2025). "IFNγ is central to anti-fungal resistance against systemic candidiasis as the IFNγ knockout mice are highly susceptible to disseminated C. albicans infection." (PMID 38787374, 2024). "The importance of IFNγ in systemic candidiasis has been well depicted in experimental murine model, wherein IFNγ deficiency in knockout mice increases their susceptibility to this infection." (PMID 33608410, 2021). "In particular, the use of emapalumab, which blocks IFNγ, may lead to increased susceptibility to infections such as systemic candidiasis, potentially contributing to adverse outcomes." (PMID 40407638, 2025). "It is well documented that candidiasis triggers type 3 responses initiated by activated IL-17-secreting cells These responses have been linked to tumor-promoting infiltrates of inflammatory cells and pose an antagonistic action to interferon-gamma (IFN-γ), a recognized anti-cancer defense mechanism." (PMID 38550775, 2024). "Consistent with our data, IFNγ knockout mice are highly susceptible to disseminated C. albicans infection, and recombinant IFNγ treatment is reported to protect them against systemic candidiasis." (PMID 38783167, 2024). "The higher levels of specific TNFα/IFNγ-producing cells suggest a robust Th1 immune response, which is beneficial for controlling invasive Candida infections." (PMID 38904363, 2024). "Disseminated candidiasis significantly increased IFNγ, WBC, and AL counts but affected IL10 insignificantly." (PMID 36477491, 2022). "We should note that IFNγ, one of the most crucial cytokines for efficient host defence for systemic candidiasis, decreased compared to DMSO after stimulation with Candida conidia (P = 0.057) for 48 hours at 200 μM of MAP3K8 inhibitor." (PMID 28727728, 2017). "Because NK cells are important modulators for potentiating phagocytes’ antifungal mechanisms by IFNγ secretion in Candida infections, we last sought to reaffirm if NK cells are required to regulate the production of IFNγ in this infection." (PMID 33608410, 2021). "Furthermore, it has been demonstrated that administration of IFNγ increases neutrophils’ and macrophages’ phagocytic and fungal killing capacity, which in turn improves patients’ resistance against invasive candidiasis." (PMID 33608410, 2021). "Furthermore, IFNγ another pro-inflammatory cytokine is thought to play a dual role during candidiasis." (PMID 22114559, 2011). "Similarly, this mutant elicited a poor serum pro-inflammatory cytokine response as judged by IFNγ and TNFα levels and showed reduced virulence in a mouse model of systemic candidiasis." (PMID 22114559, 2011). "Bozza and colleagues reported that CD4+CD25+ regulatory T cells in candidiasis are strictly dependent on the expression of B7 costimulatory molecules by IL-10-producing DCs, and are involved in the IFNγ/IDO-dependent pathway that controls the local inflammatory pathology." (PMID 18221522, 2008). "Furthermore, IL-12 regulates T cell proliferation and differentiation, with IL-2 enhancing interferon-gamma (INF-γ) production through the januskinase signal transducer and transcription factor (JAK-STAT) pathway during Candida infection." (PMID 38605952, 2024). "Another study that corroborated the beneficial role of IFNγ in Candida immunity was the protection elicited by the adoptive transfer of IFNγ-producing Th1 cells, but not IL17-producing Th17 cells, against systemic candidiasis." (PMID 33608410, 2021).
graft versus host disease (46 papers, 2010 to 2025). An immune system disorder that occurs after allogeneic hematopoietic stem cell transplant and is a reaction of donor immune cells against host tissues. "In particular, we explored the enhancing effect of CsA on IFNγ pre-licenced MSC capacity to suppress pathogenic T cell responses and prolong survival in an humanised mouse model of acute graft versus host disease." (PMID 33853687, 2021). "The authors reasoned that IFNγ produced by FOXP3+ Treg cells has essential immunosuppressive functions that are required for the prevention of experimental graft-versus-host disease, which hints at a more universal function of this cytokine beyond its role in classical Th1-type immune responses." (PMID 35225986, 2022). "Similar to radiation-induced bone marrow aplasia, elevated or prolonged IFNγ has been suggested to cause bone marrow failure in aplastic anemia, HIV and graft-versus-host diseases, by modifying cytokine responses and expression of genes involved in hematopoietic stem cell proliferation." (PMID 36668761, 2022). "This phenomenon of IFNγ-secreting Foxp3+ cells is further supported and extended in a recent study identifying that IFNγ secretion by Foxp3+ cells was necessary for their regulatory function in a model of graft-versus-host disease." (PMID 23345540, 2013). "Importance of IFNγ to the immunosuppressive capacity of MSC is highlighted by the fact that MSC from IFNγR1−/− mice are unable to prevent graft versus host disease (GVHD) in contrast to MSC from WT mice." (PMID 26779185, 2015). "We here introduce two highly robust animal models of immune pathology: 1) acute radiation syndrome (ARS) and 2) graft versus host disease (GvHD), in conjunction with studying the immunomodulatory effect of well-characterized Interferon gamma (IFNγ) primed bone marrow derived MSCs." (PMID 34386012, 2021). "Interferon-gamma regulates idiopathic pneumonia syndrome, a Th17+CD4+ T-cell-mediated graft-versus-host disease." (PMID 23843069, 2013). "Importantly, CsA exposure to IFNγ pre-stimulated MSC before administration, significantly enhanced the potency of MSCs in a human relevant humanised mouse model of acute Graft versus Host Disease." (PMID 33853687, 2021).
airway hyperresponsiveness (45 papers, 2005 to 2025). "Assessments of respiratory resistance (Rrs) and lung compliance (Cst) by FlexiVent affirmed a significant improvement of airway hyperresponsiveness and lung fibrotic change post IFNγ and IFNα signaling blockade." (PMID 41446064, 2025). "RSV shifts the immune system toward a Th2 profile, reducing IFN-γ (Interferon gamma) production and enhancing airway hyperresponsiveness." (PMID 41153509, 2025). "MiRNA-9 levels were synergistically increased following IFNγ/LPS co-exposure in isolated macrophages and in vivo, in an IFN-γ/LPS–induced mouse model of steroid-resistant airway hyperresponsiveness (AHR)." (PMID 31071965, 2019). "It has been shown, that in IFNγ knockout mice less pronounced allergic symptoms such as antigen-specificIgE, eosinophilic infiltration, and airway hyperresponsiveness occur." (PMID 15833106, 2005). "TNFα/IFNγ augmented the expression of several genes that were also corticosteroid insensitive including, CD38, a Ca2+ regulatory protein that contributes to ASM hypercontractility and airway hyperresponsiveness." (PMID 35578269, 2022). "DiABZI administration during HDM challenge increased airway hyperresponsiveness, neutrophil recruitment with prominent NOS2+ARG1− type 1 neutrophils, protein extravasation, cell death by PANoptosis, NETs formation, extracellular dsDNA release, DNA sensors activation, IFNγ, IL‐6 and CXCL10 release." (PMID 39466641, 2025). "LPS-reduced HDE challenge induced significantly higher concentrations of IFNγ, and IL-5 and IL-13 in the BAL fluid, but did not decrease airways hyperresponsiveness or airway resistance to methacholine challenge." (PMID 21345191, 2011).